CXCR4 (C-X-C motif chemokine receptor 4)
Diseases named in the same sentence as CXCR4 in open-access papers (continued):
Sharing a sentence is not in itself a finding about the gene and the disease.
cancer (continued). "CXCR4 is a potential mediator that induces cytotoxic T-lymphocyte exclusion and participates in resistance to anti-PD-1 therapy of cancer." (PMID 31815619, 2019). "Some signaling pathways such as Wnt/β-catenin and PI3K-AKT are reported to contribute to the CXCR4-mediated invasion and angiogenesis in cancers." (PMID 30678736, 2019). "Among the cancer stem cell candidates, the fold change in the CXCR4 expression was the highest following hypoxia treatment (BEAS-2B 11.88424 and A549 6.338601)." (PMID 30760238, 2019). "Here, we demonstrate that functional crosstalk between PDGFR/SDF-1 pathways induces the autocrine activation of SDF-1/CXCR4 signaling in cancer cells of mouse and human PD/S-SCCs, which promotes distant metastasis." (PMID 30874597, 2019). "Altogether, our data indicates that lead anti-CXCR4 ADC 713 is also efficacious in NSCLC models and demonstrates high specificity towards CXCR4+ cancer cells." (PMID 30792442, 2019). "The optimal ADC selectively eliminated CXCR4+ cancer cells in solid tumours, but showed limited toxicity to normal CXCR4+ tissues, sparing haematopoietic stem cells and progenitors." (PMID 30792442, 2019). "ACKR3 generally is not considered a chemotactic receptor, however, addition of CXCL12 enhances ACKR3+/CXCR4+ cancer cell migration across endothelial cells toward CCL19 and CXCL13, chemokines expressed by endothelial cells inside the lymph nodes." (PMID 30800123, 2019). "CXCR4, encoding a CXC chemokine receptor specific for stromal cell-derived factor-1, plays an important role in cancer progression and migration." (PMID 30430424, 2019). "Targeting chemokine interactions and subsequent recruitment of macrophages within tumors, including the CCL2/CCR2 or CXCL12/CXCR4/7 chemokine-chemokine receptor axes, have shown great potential for cancer therapies in various mouse models of cancer metastasis." (PMID 30832375, 2019). "The CXCL12/CXCR4 system is overexpressed in a large variety of tumors, and this axis has been increasingly identified as an important target in cancer growth, metastasis, relapse, and resistance to therapy." (PMID 31304688, 2019). "Another important mediator of cancer cell homing and bone metastases is the G-protein-coupled chemokine receptor, CXCR4." (PMID 31877673, 2019). "Studies have found that CD164 overexpression promotes cancer cell migration by activating the CXCR4/PI3K/AKT/mTOR axis." (PMID 31007847, 2019). "These cells express two prominent markers—the oncogene EWS/FLI1 and the chemokine receptor CXCR4, which is used as a target of treatment in several types of cancer." (PMID 31810195, 2019). "Conversely, the activation of CXCR4 in non-small-cell lung cancer suggests that there is a cell-type specific enrollment of subtypes in different cancers." (PMID 30791675, 2019). "Here, we demonstrate that PDGFR signaling induces SDF-1 expression and the autocrine activation of SDF-1/CXCR4 signaling in cancer cells and L-CSCs, which promotes the invasion capability of these cells and lung metastasis in mouse and human PD/S-SCCs." (PMID 30874597, 2019). "On the other hand, the role of the neutrophilic CXCR4 signaling in driving cancer invasion and metastasis formation is poorly understood." (PMID 30787324, 2019). "The upregulation of C-X-C chemokine receptor type 4 (CXCR4) is another strategy adopted by cancer cells to find protection within the BM niche." (PMID 31861268, 2019). "These ECMR pathways were associated with a significantly increased expression of genes involved in the CXR/CCL chemokine pathway, including CD44 and CXCR4 which are cancer stem-cell markers." (PMID 31874999, 2019). "It is established that cancer cells expressing CXCR4 home to secondary organs where CXCL12 is highly secreted, mainly by mesenchymal stromal cells." (PMID 30787324, 2019). "Contrary to other drugs targeting CXCR4, anti-CXCR4 ADCs effectively eliminated cancer cells as monotherapy, while minimizing leucocytosis." (PMID 30792442, 2019).
cancer (continued). "First of all, the CXCL12/CXCR4 interaction is critical for the recruitment of metastatic cancer cells into the bone marrow niche, since these cells, by expressing CXCR4, essentially hijack the homing mechanism for hematopoietic cells." (PMID 31572390, 2019). "Despite SDF-1-driven intracellular signals via CXCR4 have been widely demonstrated in the regulation of cancer cell homing to the bone, the role of CXCR7 is still debated." (PMID 31324252, 2019). "Knockdown of RhoA expression increases CCR5 and CXCR4 transcripts in 4T1 cancer cells suggesting a possible transcription-regulatory function of RhoA." (PMID 31705019, 2019). "CXCR4 is an interesting molecule that is associated with HIV infection, cancer, stem cell proliferation, differentiation, and migration." (PMID 30791675, 2019). "There are now over 2,400 publications describing a role for CXCR4 in cancer and over 300 publications describing a role for CXCR2 in cancer progression." (PMID 30873179, 2019). "CXCR4 is one of 23 known human chemokine receptors, which plays a key role in leukocyte trafficking, hematopoiesis, organ development and cancer metastases." (PMID 31787895, 2019). "Functionally and mechanistically, circFGFR1 promotes the progression and immune system evasion of NSCLC cells by sponging miR-381-3p and targeting CXCR4, which has been identified as a critical oncogene in several cancers." (PMID 31815619, 2019). "CXCR4+ haematological and solid tumour cells co-opt the role of CXCL12/CXCR4 in development and the “homing” of cancer cells to bone marrow is associated with therapy resistance and poor prognosis." (PMID 30792442, 2019). "CXCR-4 is expressed in many hematological malignancies and is thought to have a role in cancer cell survival." (PMID 31544840, 2019). "The role of CXCL12/CXCR4 on chemotaxis in various cancers is vital to the development of metastases, as evidenced by CXCR4-expressing cancer cells migrating via chemotaxis through a CXCL12 gradient to form metastatic lesions 33-35." (PMID 31534521, 2019). "Of particular interest is the potential exploitation of the CXCR4-SDF-1 axis due to its prominent roles in regulating the migration of many types of cancer cells." (PMID 31456685, 2019). "On the other hand, gemcitabine exposure of these cancer cells induced the increase of CXCR4 protein expression." (PMID 31275385, 2019). "CXCR4 and its ligand stroma derived factor 1 (SDF1) are up-regulated in various cancers, and CXCR4 inhibition prevented metastasis formation." (PMID 31481958, 2019). "CXCR4/SDF-1 interaction has been shown to mediate the homing and quiescence of hematopoietic stem cells (HSCs); however, in cancer, CXCR4-positive cells are more prone to metastasis." (PMID 29478325, 2019). "CXCR4 expression is deregulated in 23 cancers and has been shown to increase cancer cell metastasis toward CXCL12 expressing cells (Balkwill, 2004a,b)." (PMID 31139626, 2019). "Studies in mice show that CXCR4 is a good target in cancer as its blockade impairs the spread of cancer cells and metastasis in several cancer models." (PMID 31507535, 2019). "Activation of CXCL12/CXCR4 not only is involved in the migration of monocyte but also the migration of T cell 30, dendritic cell 31, neuronal cell as well as cancer cell." (PMID 29105376, 2018). "We next used the CXCR4+ luciferase+ SW1417 SC CRC model to assess if the selective CXCR4+ cancer cell killing induced by T22‐GFP‐H6‐FdU treatment in vivo was capable of blocking spheroid formation in vitro." (PMID 30190334, 2018). "Recently, the overexpression of chemokine (C-X-C motif) receptor 4 (CXCR4) has been verified in a variety of cancers, leading to the development of targeted PET tracer such as 68Ga-Pentixafor." (PMID 29531504, 2018). "B-cells, MM cells, and other bone metastatic cancer cells, including breast and melanoma cells, express CXCR4, which functions in the proliferation and migration of these cells to the SDF1-rich BMM." (PMID 30671025, 2018).
cancer (continued). "The CXCL12/CXCR4/ACKR3 axis is frequently hijacked by cancer cells to promote their survival, growth, resistance to chemotherapy, metastasis and immune evasion." (PMID 30257500, 2018). "CXCL12/CXCR4 axis has been shown to play a significant role in prostate cancer and promoted cancer metastasis." (PMID 30723697, 2018). "CXCR4 is the first identified receptor for CXCL12, and it is generally recognized that the CXCL12/CXCR4 axis participates in many aspects of cancer, such as the angiogenesis, metastasis, and the survival of cancer cells." (PMID 30574021, 2018). "The role of CXCL12/CXCR4 in cancer cell trafficking to bone has been explored extensively; however, there is a potential function for this pathway in modulating OCLs and bone resorption." (PMID 29930538, 2018). "This new approach is expected to highly enhance its clinical impact in CRC and other cancer types in which CXCR4 mediates metastasis development." (PMID 30190334, 2018). "Mounting evidence has shown that CXCR4 is involved in the process of different nociceptive responses such as neuropathic pain or cancer pain in glial cells of the dorsal root ganglion (DRG) or in the spinal cord." (PMID 29386025, 2018). "Given the pleiotropic role of CXCR4 in cancer biology, we anticipate continuous interest in this target, particularly in the testing of therapeutic combinations for immuno-oncology." (PMID 29554149, 2018). "Hypoxia selectively augments CXCR4 expression through HIF-1 activation in several cell types including cancer cells." (PMID 29098360, 2018). "Among the SNV top-ranked promoters (DMD), DHS elements (LRMP) and enhancers (PAX5, BACH2, BCL2, CXCR4, and BCL7A) are highly cancer-type-specific cases with many BCL or CLL mutations." (PMID 29354286, 2018). "As a result, CXCR4 expression more directly reflects the biological characteristics of cancer cells." (PMID 29783989, 2018). "In primary skin tumors, cancer cells express CXCR4, a chemokine receptor involved in bone marrow homing and cell retention." (PMID 30420855, 2018). "Remarkably, the success of CXCR4 inhibitors in the field of hematological malignancies is attributed in part to their potential to mobilize cancer cells into the circulation and thus render them more chemo-sensitive." (PMID 30257500, 2018). "Nevertheless, these reports strongly suggest a pro-metastatic function of SDF-1/CXCR4 signaling in several cancer entities." (PMID 30622535, 2018). "For example, CXCL12/CXCR4 axis promoted stem-like properties, metastatic potential, and radiation resistance in cancer cells." (PMID 30723697, 2018). "Given its prominent role in inflammation and cancer biology, the C-X-C motif chemokine receptor 4 (CXCR4) has gained a lot of attention in the recent years." (PMID 30105558, 2018). "It has been proposed that deleterious impact of CXCR4 expression in cancer cells is due to its pro-proliferative role." (PMID 30181898, 2018). "For example, as demonstrated in several studies, SDF-1 chemoattracts CXCR4+ cancer cells to bone, which leads to initiation of bone metastases." (PMID 30375490, 2018). "Since the discovery of ACKR3 as a CXCL12-binding chemokine receptor in addition to CXCR4, its role in several cancers has been explored but its effects are still the source of many conflicting reports." (PMID 30441765, 2018). "Recently, CXCR4 has been shown to play an important role in invasion, angiogenesis, and metastasis, contributing to tumorigenesis and cancer progression." (PMID 29636841, 2018). "A small-molecule inhibitor of CXCR4, plerixafor (Mozobil), will be investigated in patients with advanced cancers, including ovarian (ClinicalTrials.gov identifier: NCT02179970)." (PMID 30445726, 2018). "This targeted drug delivery approach yields potent antimetastatic effect, through selective depletion of metastatic CXCR4+ cancer cells, and validates metastatic stem cells (MetSCs) as targets for clinical therapy." (PMID 30190334, 2018).
cancer (continued). "Combined, these examples suggest that CXCR4 expression by cancer cells contribute to their tropism to metastatic niches." (PMID 30622535, 2018). "CXCL12 is the only ligand for CXCR4 and acts as autocrine/paracrine growth factor for several cancers." (PMID 30564115, 2018). "High expression of the serum response factor in stromal fibroblasts induces cancer cell metastasis by CXCL12/CXCR4 signaling." (PMID 29883428, 2018). "For example, CXCR4 is co-expressed with NeuN in the spinal cord of cancer-induced bone pain rats or incision-induced postsurgical pain rats." (PMID 29386025, 2018). "We next used the same SC SW1417 CRC model to assess if the selective internalization into the cytosol of CXCR4+ target cancer cells achieved by the nanoconjugate led to selective FdU delivery." (PMID 30190334, 2018). "With downregulation or upregulation of AnnexinA7, the expression levels of SDF1/CXCR4 are uniformly decreased or increased in cancer cells in vitro and in vivo." (PMID 29783989, 2018). "These and other observations strongly suggest SDF-1/CXCR4 signaling as promising target in anti-cancer therapy, in particular, in combination with radiation therapy." (PMID 30622535, 2018). "CXCR4 plays an important role in immunity, organogenesis and repair, anti-cancer, embryonic development, and hematopoiesis." (PMID 29562634, 2018). "These functions contribute to malignancy, progression and therapy resistance of the tumors and render SDF-1/CXCR4 signal to an ideal target in anti-cancer therapy." (PMID 30622535, 2018). "The LDGI‐loaded MSCs with high CXCR4 expression maintained good bioactivity to migrate to the cancer cells in vitro and in vivo." (PMID 30356957, 2018). "We found that CXCL12 – CXCR4 signaling induces sensitivity of the cancer cells to specific molecular inhibitors of MAPK and PI3K pathways, preventing proliferation of TNBC cells." (PMID 29416611, 2018). "In parallel, the field of CXCR4-based diagnostics and therapeutics for cancer have evolved significantly." (PMID 30257500, 2018). "It is therefore not surprising that divergent signaling and cellular responses are being observed, among different cancers but also within a particular cancer type and uniform CXCR4 expression." (PMID 29776413, 2018). "This is in particular interesting, since previous in vitro studies have reported high CXCR4 expression in this aggressive cancer subtype." (PMID 30191351, 2018). "The chemokine receptor, CXCR4 is expressed in over 30 types of malignant tumors and, through interaction with its ligand CXCL12, was shown exert pleotropic pro-tumorigenic effects." (PMID 30257500, 2018). "The various transduction pathways activated by the SDF-1/CXCR4 axis have been extensively studied in adherent normal and cancer cells." (PMID 30373149, 2018). "Chemokine receptor CXCR4 and its ligand CXCL12 (SDF‐1) have shown to be overexpressed in more than 20 solid tumors and CXCR4 serves as a Cancer Stem Cell (CSC) marker in multiple cancers." (PMID 29460395, 2018). "The rate of high CXCR4 expression was significantly greater in carcinomas overexpressing AIB1 (58/83 cases, 69.9%) than in those cases with a normal expression of AIB1 (23/73 cases, 31.5%, P < 0.001)." (PMID 30103827, 2018). "High CXCR4 expression characterize cancer cells with high migratory capability and biological aggressiveness." (PMID 28566721, 2017). "High levels of SDF-1 and CXCR4 in malignant ascites, and in the tumors and sera of OVC patients correlate to drug resistance, poor disease prognosis, and metastasis." (PMID 28196146, 2017). "Interruption of the CXCL12/CXCR4 axis using CXCR4 inhibitor AMD3100 or neutralizing CXCR4 antibodies blocked the progression of cancer metastasis." (PMID 28176874, 2017). "Determining expression of CXCR4 in individual tumors would be valuable for investigating the significance of CXCR4 in ACC and other cancers, and for selecting patients for studies using CXCR4-targeting therapies." (PMID 29088715, 2017).
cancer (continued). "It promotes the expression of several pro-tumorigenic genes such as CXCR4, which is crucial for cancer cell migration and invasion." (PMID 27213582, 2017). "Expression of the chemokine receptor CXCR4 by many cancers correlates with aggressive clinical behavior." (PMID 29088715, 2017). "We also detected other cancer stem cell-related genes in the putative A549 stem cells, and found that CXCR4, NESTIN, BMI1 gene levels had increased." (PMID 28881812, 2017). "Treatment with plerixafor is also capable to sensitize prostate cancer cells and pancreatic cancer cells to chemotherapy and it is believed that attachment of CXCR4 expressing cells to the ECM protects cancer cells from chemotherapy." (PMID 28402937, 2017). "Taken together, these data clearly demonstrate that SIK3 mediates pro-metastatic CXCR4 expression following high salt and IL-17 induction to cancer cells." (PMID 28658303, 2017). "Recent studies reported that CXCR4 induced cancer cell migration and invasion by activating AKT, ERK, Jak2, and Stat3." (PMID 29069741, 2017). "CXCL12/CXCR4 is known to regulate the critical steps of cancer invasion and metastasis; therefore, EC cells with increased CXCR4 expression have a high metastatic ability." (PMID 29383153, 2017). "SDF-1/CXCR4 signaling axis determines the proliferative potential and site-specific cancer metastasis." (PMID 28938623, 2017). "Repetitive i.t. administration of CXCR4 siRNA remarkably suppressed TCI-induced cancer pain behaviors (mechanical allodynia, thermal hyperalgesia, spontaneous flinching and loss of limb use), which is consistent with our previous findings." (PMID 28638088, 2017). "From the initial studies of CXCR4 in cancer there has been a focus on the role of the receptor in metastasis." (PMID 29088715, 2017). "Anti-CXCR4 antibodies have been shown to inhibit CXCL12 mediated cancer cell adhesion, migration, and proliferation." (PMID 28890883, 2017). "We previously demonstrated that the chemokine receptor CXCR4 plays an important role in cancer-induced bone pain by activating spinal neurons and glial cells." (PMID 28638088, 2017). "CXCL12 is a key attraction and retention signal for stem cells including cancer stem cells via activation of its receptor CXCR4." (PMID 28423491, 2017). "Previously, we found that the downregulation of UHRF1 leads to the induction of EMT via CXCR4 in human cancer cells." (PMID 28584306, 2017). "The peritoneum can attract CXCR4‐positive cancer cells to migrate toward and seed on through a CXCL12 gradient secreted by mesothelial cells." (PMID 28544785, 2017). "The CXCR4 ligand CXCL12 is mainly expressed by mesenchymal stromal cells in liver, lungs and bone marrow (BM) where CXCR4-positive cancer cells can be recruited to initiate metastasis." (PMID 28566721, 2017). "Inhibition of CXCR4-mediated signaling has therapeutic efficacy by itself, but can also have a synergistic effect with other anti-cancer drugs, such as bortezomib, melphalan, doxorubicin, and dexamethasone." (PMID 27896627, 2017). "The seven pathways comprised the EIF2 pathway, RAR activation, CXCR4 pathway, molecular mechanisms of cancer, protein kinase A signaling, factors promoting cardiogenesis in vertebrates, and Fcγ receptor-mediated phagocytosis in macrophages and monocytes." (PMID 28293639, 2017). "Collectively, these results suggest that the CaMKII/CREB pathway in spinal neurons mediates CXCR4-facilitated pain hypersensitivity in cancer rats." (PMID 28638088, 2017). "First, the upregulation of CXCL12/CXCR4 axis and activation of downstream pathways and their biological functions in proliferation, invasion, and migration of cancer cells are similar." (PMID 28544785, 2017). "Several lines of evidence have conclusively suggested that expression of chemokine CXCL12 and its specific receptor CXCR4 on cancer cells promote metastasis." (PMID 28658303, 2017).